CD4 (CD4 molecule)
Diseases named in the same sentence as CD4 in open-access papers (continued):
Sharing a sentence is not in itself a finding about the gene and the disease.
myositis (continued). "In this study, with the aim to differentiate involvement of CD4+ and CD8+ T-cell subpopulations in myositis subgroups, we investigated transcriptomic profiles of T cells from peripheral blood of patients with myositis." (PMID 30157932, 2018). "We found that PI4KAP1 had a higher expression in CD4+ T cells of HLA-DRB1*03-positive myositis and that TRGC2, CTSW, HPCAL4, ZNF683, and GOLGA8B had a higher expression in CD4+ T cells of HLA-DRB1*03-negative myositis patients." (PMID 30157932, 2018). "The muscle disease is characterized by myofiber necrosis/regeneration and an inflammatory infiltrate composed of CD4+ T-cells, CD8+ T-cells, and myeloid cells, resembling human myositis." (PMID 28424681, 2017). "Given the residual T cell infiltration in CD4-Cre.MyD88fl/fl conditional KO mice immunized with recombinant HRS, we next addressed the relative role of TCR-mediated, adaptive immune signaling pathways in driving HRS-induced myositis." (PMID 37809058, 2023). "At the second analytical stage, we found that although HLA-DRB1*03-positive and -negative myositis are not separated by the first PCs, 12 genes were differentially expressed in CD4+ T cells in comparison of myositis patients with different genotypes." (PMID 30157932, 2018). "We have demonstrated that a majority of CD28null T cells (89 % of the CD4+CD28null and 98 % of the CD8+CD28null T cells) in the circulation of patients with myositis stained positive for CD244 and strong correlations were observed between CD244+ cells expressing CD3+ and CD28null T-cell subsets." (PMID 27039301, 2016). "Relative quantification of proteasomal subunit expression by real time RT-PCR revealed a myositis related significant increase of at least one of the immunoproteasomal subunits PSMB8, PSMB9 and/or PSMB10 in all investigated cellular subsets except CD4+." (PMID 25098831, 2014). "Moreover, removal of class I MHC significantly suppressed myositis and the adoptive transfer model suggested that the CD8 T cell-induced muscle injuries were significantly more severe than the CD4 T cell-induced muscle injuries." (PMID 24939012, 2014). "Of interest, depletion of both CD4 and CD8 T cells suppresses the myositis phenotype in this model." (PMID 25161767, 2014). "Therefore, we searched for differentially expressed genes between HLA-DRB1*03-positive and -negative myositis patients in CD4+ T cells." (PMID 30157932, 2018). "However, the adoptive transfer of functional CD4+ T-cells did not restore the second phase of hypophagia occurring during nurse cell formation-induced myositis." (PMID 23349631, 2013). "Therefore CD4+ T-cells are not sufficient for this secondary hypophagic period, during T. spiralis induced myositis." (PMID 23349631, 2013). "Comparison of HRS-induced myositis in WT versus CD4-Cre.MyD88fl/fl conditional KO mice demonstrates significant reduction in the severity of myositis that reflects diminished infiltration of both CD3+CD4+ T cells and CD3-CD4-CD45+ non-lymphoid cells that include CD68+ macrophages." (PMID 37809058, 2023). "In contrast, TIF1γ‐induced experimental myositis is primarily driven by CD8+ T cells and type I IFN signaling, independent of CD4+ T cells or B cells." (PMID 41357670, 2025). "Although we did not classify patients with IIM based on specific myositis antibody subtypes to compare levels of exhausted T cells (owing to limited sample size), we observed increased expression of LAG‐3 and TIM‐3 in both CD4+ and CD8+ T cells in IIM." (PMID 39284778, 2024).
neuropathy (31 papers, 2010 to 2025). A disorder affecting the nervous system that manifests with pain, tingling, numbness, and/or muscle weakness. "In contrast, few reports involving children and adults during ART era have not shown association between immunosuppression and advanced disease with PN despite several studies suggesting that low CD4 cell counts represents a risk factor for HIV neuropathy." (PMID 34388988, 2021). "Decreased CD4+ count correlates with worsening immunological status, which is associated with neuropathy in HIV patients." (PMID 30045275, 2018). "Among the factors independently associated with the development of neuropathy or pancreatitis, we found a low CD4 cell count nadir, a common marker for most toxicities and co-morbidities." (PMID 23468971, 2013). "In “mix-and-match” adoptive transfer experiments, in which CD4+ and CD8+ T cells were either from IL-21R–sufficient or IL-21R-deficient NOD.AireGW/ mice, a modest delay in the development of neuropathy was noted when CD4+ T cells were IL-21R deficient." (PMID 39087473, 2024). "Significantly higher CD4+ T-cell counts and a lower likelihood of randomization to the ddI/d4T arm were observed among individuals with later onset of neuropathy (≥259 days)." (PMID 33057367, 2020). "In conclusion, we show for the first-time dysregulated patterns of neuropathy-specific cytokine/chemokine profile and an altered phenotype of circulating CD4+ T cell subpopulations with enhanced CD4+ memory T cell frequency in CTS patients." (PMID 28811623, 2017). "Neuropathy is a common complication of HIV and is associated with advanced immunosuppression and low CD4 cell counts and has been used as a predictor of death in resource limited settings." (PMID 28705181, 2017). "Notably, HIV-infected patients who develop neuropathy tend to have lower CD4 count, indicative of advanced disease progression." (PMID 39705222, 2024). "Moreover, WT female mice had significantly more CD4+ T cells in the DRG 14 days post-PTX than cHET female mice, implicating a potential role for CD4+ T cells in the resolution of CIPN and/or susceptibility to future neuropathy." (PMID 38330029, 2024). "However, in the course of neuropathy, the CD4+ and CD8+ T helper cells are unchanged in the spinal cord, in contrast to strongly activated glial cells." (PMID 36618360, 2022). "In the group without neuropathy, only the domain of social aspects showed a statistically significant association in relation to CD4." (PMID 35946704, 2022). "Higher sTFR or iron stores, the HFE 187C>G variant, and lower baseline hsCRP were associated with significantly delayed neuropathy in self-reported whites (n = 28; all p-values<0.05), independent of age, CD4+ T-cell count, plasma HIV RNA, and cART regimen." (PMID 33057367, 2020). "Finally, while rates of incident, symptomatic neuropathy in PWH may be significantly lower when the CD4+ T-cell count is >250 and newer antiretroviral drugs are initiated, these findings may not apply to areas where nutritional deficiencies, which contribute to neuropathy risk, are endemic." (PMID 33057367, 2020). "Thus, CD4 T-cell induced neuropathy in the corneas and lacrimal glands of Aire -/- mice display both structural and functional changes consistent with the human disease." (PMID 28926640, 2017). "In particular, an important infiltration of pro-inflammatory CD4+ lymphocytes occurs in the leptomeninges of the dorsal root ganglia in neuropathic pain model or in spinal meninges in CSF1 neuropathy-mimicking model, which may interact with microglia to modulate mechanical hypersensitivity." (PMID 37860691, 2023). "The experimental group treated with anti–IL-21R antibody showed a decreasing trend in the incidence of neuropathy, electromyography (EMG) abnormalities, and CD4+ T cell infiltration." (PMID 39087473, 2024).
neuropathy (continued). "Additionally, we demonstrate that IL-21 signaling was required for neuropathy development and that IL-21 upregulated CXCR6, a chemokine that promotes CD4+ T cell localization within peripheral nerves." (PMID 39087473, 2024). "Moreover, CD4 and IL-21 staining was absent in the non-neuropathic controls (NOD.WT), which suggests that the neuropathy was associated with increased IL-2–producing CD4+ T cells in peripheral nerves." (PMID 39087473, 2024). "Although there is support for spinal cord-infiltrating CD4+ T lymphocytes in contributing to neuropathic pain due to spinal nerve transection injury, chemotherapy-induced neuropathy does not appear to be influenced by either this cell type or the CXCR4 antagonist AMD3100." (PMID 22998838, 2012).
retinitis (31 papers, 2011 to 2025). Inflammation of the retina. "They all had a history of low CD4 T cells and a subsequent good immunological response, indicating the immune recovery retinitis caused by the immune response of CMV infection." (PMID 35573011, 2022). "Most patients had a CD4 lymphocyte count less than 50/μL, which can represent the susceptibility to this type of retinitis when lymphocyte count falls below this threshold." (PMID 25408732, 2014). "Even in two patients with CD4 T cell counts above 400 cells/μl, recurrent CMV-related retinitis correlated with the loss of HCMV-specific CD4 T cells." (PMID 23717308, 2013). "Retinopathy and retinitis were strongly linked with CD4-positive counts of fewer than 200 cells/mL." (PMID 37763724, 2023). "In their report, two patients had vitritis that was noted early in the course of the retinitis, and the vitritis occurred in patients who have a history of very low CD4 counts before HAART initiation." (PMID 35573011, 2022). "Retinitis in inflamed eyes usually occurs in patients with higher CD4+ counts and is more commonly due to acute retinal necrosis, toxoplasmosis, syphilis, or late stages of Cryptococcus spp." (PMID 25741521, 2014). "Retinitis in quiet eyes occurs in patients with lower CD4+ counts and is more commonly due to cytomegalovirus (CMV) and progressive outer retinal necrosis." (PMID 25741521, 2014). "In this study, 21.7% of the patients were found to have CMV infection, in which 4.2% and 1.1% had found retinitis and cephalitis, and the median CD4 counts were 63.5cells/ul and 14.2cells/ul, respectively." (PMID 24204583, 2013). "At a 5-month follow-up, the area of retinitis had been resolved and the CD4+ T lymphocyte count was 169 cells/mm3." (PMID 23800125, 2013). "In this study, profound and persistent CD4+ T-cell suppression (median, 167 cells/μL) accompanied by an inverted CD4+/CD8+ ratio may represent a key risk factor for CMVR retinitis." (PMID 41179870, 2025). "The most common CMV disease among patients with uncontrolled HIV infection is CMV-Retinitis that may develop when CD4+ T-cell counts drop below 50–100 CD4+ cells/μl." (PMID 31396258, 2019). "Mortality, retinitis progression, retinal detachment, IRU, CD4+ T-cell counts, HIV viral load, AEs, and other OI incidence are defined as secondary outcomes in our study." (PMID 33736696, 2021). "The progression of retinitis in patients on HAART, even with low CD4 counts, was lesser in Western studies even though they were expected to behave like pre-HAART-era patients." (PMID 23514612, 2013). "In February the following year (year 3) the patient had a CD4+ cell count of 30 × 106/L, and CMV-retinitis was diagnosed and treated with altering foscarnet and ganciclovir." (PMID 23880011, 2013). "There is evidence that shows compromised visual function, including contrast sensitivity (CS); visual evoked potentials (VEP) and electro-retinograms (ERG); colour vision and perimetry; in PLHIV on ART without retinitis, at CD4+ counts below 200 cells/mm3." (PMID 37545934, 2023). "These log scores were still higher than those for PLHIV on ART, without retinitis, at lower CD4+ counts." (PMID 37545934, 2023). "CD4 counts are not a reliable indicator and these patients can develop retinitis and recurrences even in presence of high CD4 counts." (PMID 34611773, 2021). "Clinically, retinitis has been shown to be the predominant pathology in AIDS patients (20–30%), and it usually appears at the late stages of the syndrome in patients with low CD4 count." (PMID 32397070, 2020). "Patient No. 26, with 118 CD4 T lymphocytes/μL of blood, suffered from retinitis with severely blurred vision, and CMV pneumonitis was diagnosed in patient No. 23, who had a count of 64 CD4 T lymphocytes." (PMID 31690039, 2019). "Adoptive transfer of CD4+ T cells, but not total IgG antibodies, from diseased mice restored the progressive retinal neurodegeneration in Rag1−/− recipients." (PMID 30097565, 2018).
retinitis (continued). "Patients on regular HAART and with improved CD4 counts, when treated with systemic and/or intravitreal ganciclovir therapy, showed complete resolution of retinitis without the need for maintenance therapy." (PMID 23514612, 2013). "Previous studies assessing contrast sensitivity using the Pelli-Robson chart found that PLHIV without retinitis, on ART, with CD4+ counts below 200 cells/mm3, showed a median LogCS of 1.65, implying sub-normal changes." (PMID 37545934, 2023).
SARS-CoV infection (31 papers, 2016 to 2023). "In managing SARS-CoV infection in animal models, CD4+ T cells were noted to be more predominant than CD8+ T cells." (PMID 36901827, 2023). "For example, mice are protected from mouse adapted SARS-CoV infection by CD4 T cells and by production of IFN-γ." (PMID 38626271, 2021). "SARS-CoV infection can significantly reduce peripheral CD4+ and CD8+ T lymphocyte subsets, which is related to the onset of the disease." (PMID 33776910, 2021). "In the acute stage of SARS-COV infection, peripheral blood lymphocytes, mainly T lymphocytes, were rapidly reduced, and CD4+ and CD8+ T lymphocytes were also reduced." (PMID 34525962, 2021). "In mouse models, cross-reactive CD4+ central memory cells, generated after a SARS-CoV infection, have been shown to induce a protective T cell immune response against MERS infection." (PMID 34228322, 2021). "It was also found that the total number of T lymphocytes, CD3+, CD4+, and naive CD4+ T cells was still lower one year post-SARS-CoV infection compared to the control value." (PMID 32916812, 2020). "The adverse cases of SARS-CoV infections showed lymphopenia with characteristic decline in both CD4+ as well as CD8+ T cells." (PMID 33262955, 2020). "In the acute phase of SARS-CoV infection, rapid reduction of lymphocytes in peripheral blood, mainly T lymphocytes, was observed, and both CD4+ and CD8+ T lymphocytes were decreased." (PMID 32196410, 2020). "In SARS-CoV infection, a rapid reduction of T lymphocytes, both CD4+ and CD8+ in peripheral blood was observed, often even before any abnormal changes were observed in chest X-rays." (PMID 32916812, 2020). "Conversely, CD8 T cell depletion in early phases did not affect neutralizing antibodies or virus clearance, suggesting that a CD4-dependent virus-specific response is critical to control SARS-CoV infection." (PMID 33182268, 2020). "Interestingly, in SARS-CoV-2 infection, CD4+ T cells react to various viral proteins such as the S, N, and M proteins, whereas in SARS-CoV infection, most of CD4+ T cells dominantly recognize the S protein." (PMID 34769508, 2021). "Depletion of CD4+ T cells, but not CD8+ T cells, leads to an enhanced immune-mediated interstitial pneumonitis and delayed clearance of SARS-CoV from the lungs in a SARS-CoV-infected mouse model, demonstrating the vital role of CD4+ T cells in preventing SARS-CoV infection." (PMID 32746940, 2020). "A previous report has shown that higher number of CD4+ T cell may protect patients from developing ARDS in SARS-CoV infection." (PMID 32746940, 2020). "However, in immunocompetent patients, this condition may be transient, with the return of CD8+ T-cells boosted by effector CD4+ and memory CD4+ T-cells within 2 to 3 months, as observed in SARS-CoV infections." (PMID 36389664, 2022). "Previous studies have shown that virus-specific T cells from the severe group tended to be a central memory phenotype with a significantly higher frequency of polyfunctional CD4+ T cells and CD8+ T cells after SARS-CoV infection." (PMID 33614513, 2021). "SARS-CoV infection increases cytokine expression (e.g., IFN-γ, IL-1, IL-6, IL-10, IL-12, and IL-16) dramatically, and T lymphocytes and their CD4+ and CD8+ T cells subsets are decreased after the onset of infection." (PMID 33770147, 2021). "At least five different CD4+ T cell lineages are known (TH1, TH2, TH17, TFH, and TREG cells) with prominent roles of TH1 and TFH cells in mounting antiviral response during SARS-CoV infection." (PMID 33335518, 2020). "Peripheral T lymphocytes, both CD4+ and CD8+, are rapidly reduced in acute SARS-CoV infection hypothetically due to lymphocyte sequestration in specific target organs." (PMID 32483488, 2020). "However, there was a dramatic restoration of CD4+, CD8+ T cells, and B cells in patients who recuperated from SARS-CoV infection." (PMID 33262955, 2020).
SARS-CoV infection (continued). "Thus, based on these animal and clinical data, CD4+ T and CD8+ T cells were central to the antiviral response during SARS-CoV infection." (PMID 33335518, 2020). "Similarly, SARS-CoV-specific T cells (CD4 and CD8 T cells) can be detected at 11 and 17 years after SARS-CoV infection in the absence of detectable antibodies." (PMID 38626271, 2021).